RIPPLY2 (ripply transcriptional repressor 2)
Description:
Plays a role in somitogenesis. Required for somite segregation and establishment of rostrocaudal polarity in somites (By similarity).
Synonyms: C6orf159; dJ237I15.1; SCDO6
Tractability: No criterion of Open Targets' tractability assessment is met for any kind of drug.
Gene: Protein-coding gene on chromosome 6 (83,853,360 to 83,857,515, forward strand). Ensembl gene ENSG00000203877.
Subcellular location: Nucleus
Pathways (Reactome):
Developmental Biology: Somitogenesis
Gene Ontology:
Molecular function: protein binding
Biological process: embryonic pattern specification; negative regulation of transcription by RNA polymerase II; somite rostral/caudal axis specification; somitogenesis
Cellular component: nucleus
Genetic constraint (gnomAD): Loss-of-function variants: 13 observed, 11.27 expected, observed/expected ratio (o/e) 1.15, 90% interval 0.75 to 1.76. The upper end of that interval is the gene's LOEUF score, 1.76, which puts it in group 6 of 6, group 1 being the genes least tolerant of losing a copy. Missense variants: 142 observed, 111.49 expected, observed/expected ratio (o/e) 1.27, 90% interval 1.11 to 1.46. Synonymous variants: 56 observed, 46.16 expected, observed/expected ratio (o/e) 1.21, 90% interval 0.98 to 1.52.
Homologues: Orthologues: chimpanzee RIPPLY2 (98% identical), pig RIPPLY2 (71% identical), mouse Ripply2 (63% identical), rat Ripply2 (59% identical), zebrafish ripply1 (38% identical), tropical clawed frog ripply2.2 (35% identical), tropical clawed frog ripply2 (33% identical). Paralogues in human: RIPPLY1 (38% identical), RIPPLY3 (29% identical).
Diseases named in the same sentence as RIPPLY2 in open-access papers:
RIPPLY2 is named in the same sentence as 8 diseases in open-access papers, as found by Europe PMC text mining. Sharing a sentence is not in itself a finding about the gene and the disease. The quoted sentences say what the papers report.
spondylocostal dysostosis (3 papers, 2020 to 2024). Spondylocostal dysplasia is a rare genetic disorder characterized by defects of the bones of the spine (vertebrae) and abnormalities of the ribs. "Although RIPPLY1 has not been associated with a human developmental disease, its paralog, RIPPLY2, causes Spondylocostal Dysostosis (MIM#616566) in an autosomal recessive mode." (PMID 32815649, 2020).
autosomal recessive spondylocostal dysostosis (1 paper, 2020). "Similar with TBX6, biallelic loss‐of‐function variants in RIPPLY2 or MESP2 cause autosomal recessive Spondylocostal Dysostosis (MIM#616566 for RIPPLY2 and MIM#608681 for MESP2)." (PMID 32815649, 2020).
clubfoot (1 paper, 2024). The most common congenital deformation of the foot, occurring in 1 of 1,000 live births. "Initially, genes associatedwith clubfoot (PITX1, TBX4, HOXA9, HOXD10, HOXD12,HOXD13, HOXA9, TPM1, TPM2, COL9A1, FLNB, CASP8,CASP10, UTX, CHD1, RIPPLY2, CAND2, WNT7) werescreened for potential variants." (PMID 38952703, 2024).
endometrial cancer (1 paper, 2022). Primary or metastatic malignant neoplasm involving the endometrium (mucous membrane that lines the endometrial cavity). "RIPPLY2 represented one of the mRNAs in a five-gene signature verified to be able to predict the survival of endometrial cancer patients." (PMID 35178089, 2022).
cancer (1 paper, 2021). A tumor composed of atypical neoplastic, often pleomorphic cells that invade other tissues. "Among all these 5 DNA, GBP4, GABRA2, and RIPPLY2 were once reported in cancer research." (PMID 33350104, 2021).
RIPPLY2 also shares sentences with these, for which no sentence is quoted: genetic disorder (1 paper); spondylothoracic dysostosis (1); tumours (1).